MALAT1 (metastasis associated lung adenocarcinoma transcript 1)
Diseases named in the same sentence as MALAT1 in open-access papers (continued):
Sharing a sentence is not in itself a finding about the gene and the disease.
hepatocellular carcinoma (continued). "MALAT1 may represent a potential non-invasive biomarker for HCV-related hepatocellular carcinoma (HCC) prognosis, via sponging miR-204, miR-143, miR-195, miR-490, miR-216b, miR-146-5p." (PMID 37888204, 2023). "LINC00673, MIR4435-2HG, MALAT1, PCBP1-AS1, and LINC00152 have been reported to promote the progression of hepatocellular carcinoma, demonstrating the important oncogenic function of SE-associated lncRNAs." (PMID 36721155, 2023). "In hepatocellular carcinoma, MALAT1/NEAT2 acts as a proto-oncogene through Wnt pathway activation and transcriptional induction of SRSF1." (PMID 33799493, 2021). "Other examples include the lncRNA highly upregulated in liver cancer (HULC) has been detected in hepatocellular carcinoma (HCC), and MALAT1 which has been shown to be prognostic in early stage lung adenocarcinoma." (PMID 33014860, 2020). "The MALAT1-miR-142-3p-SMAD5 axis plays an important role in cell proliferation, migration, and invasion of hepatocellular carcinoma cells." (PMID 31168355, 2019). "The knockdown of MALAT1 inhibited proliferation, migration, invasion and EMT, and promoted cell apoptosis of hepatocellular carcinoma cells via miR-142-3p." (PMID 31168355, 2019). "The knockdown of MALAT1 inhibited the proliferation, migration, invasion, and epithelial cell-to-mesenchymal transition (EMT), and promoted apoptosis of hepatocellular carcinoma cells via miR-142-3p." (PMID 31168355, 2019). "In this study, we indicate that HULC, MALAT1 and TRF2 are highly expressed in hepatocellular carcinoma tissues, and present a positive correlation." (PMID 27782152, 2016). "To this data, we clearly identify that HULC, MALAT1 and TRF2 are highly expressed in hepatocellular carcinoma tissues, and present a positive correlation." (PMID 27782152, 2016). "In summary, we have shown that MALAT1, a non-coding RNA, was over-expressed in the sera of people exposed to arsenite and in hepatocellular carcinomas (HCCs), and MALAT1 had a close relation with the clinicopathological characteristics of HCC." (PMID 26735578, 2016). "Our results demonstrate HULC, MALAT1 and TRF2 are highly expressed in human hepatocellular carcinoma tissues, and HULC plus MALAT1 overexpression drastically promotes the growth of liver cancer stem cells." (PMID 27782152, 2016). "In addition, MALAT1 was originally discovered to be a marker for metastasis development in early stage lung adenocarcinoma, and more recently it was shown to be a metastasis-related marker both in squamous cell carcinoma of the lung and hepatocellular carcinoma." (PMID 27777857, 2016). "Recently, several studies have demonstrated that two long non-coding RNAs (lncRNAs), HULC and MALAT1, may participate in hepatocellular carcinoma (HCC) development and progression." (PMID 22493738, 2012). "However, the underlying mechanism of MALAT1 in hepatocellular carcinoma (HCC) has not been thoroughly elucidated." (PMID 37653482, 2023). "MALAT1 and Taurine upregulated gene 1 (TUG1), which are upregulated in various tumours including HCC, colorectal cancer (CRC), breast cancer, glioblastoma, and hepatocellular carcinoma promote angiogenesis by increasing VEGF expression through sponging miRNAs." (PMID 35052495, 2022). "Also, a positive feedback loop between MALAT1 and HIF-2α was discovered in arsenite induced hepatocellular carcinomas." (PMID 34012919, 2021). "MALAT1 and VEGF-A expression is up-regulated in hepatocellular carcinoma (HCC)." (PMID 34209679, 2021). "In addition, lncRNA MALAT1 modulated miR-125a-3p to increase FOXM1 expression, resulting in hepatocellular carcinoma progression." (PMID 33539420, 2021). "Accumulating evidence has revealed that MALAT1 enhances the expression of serine arginine-rich splicing factor 1 (SRSF1) and activates the mammalian target of rapamycin (mTOR) signaling pathway in hepatocellular carcinoma (HCC)." (PMID 34001131, 2021).
hepatocellular carcinoma (continued). "In our study, we confirmed that MALAT1 was upregulated in hepatocellular carcinoma tissues compared with adjacent non-tumor tissues." (PMID 31168355, 2019). "The expression of MALAT1 and miR-142-3p in hepatocellular carcinoma tissues, cell lines and adjacent non-tumor tissues was assessed by Q-PCR." (PMID 31168355, 2019). "Firstly, we assessed the relative expression level of MALAT1 in hepatocellular carcinoma tissues and adjacent non-tumor tissues." (PMID 31168355, 2019). "Notably, all the hepatocellular carcinoma cell lines—especially the two lines (HepG2, SMMC-7721)—had a higher level of MALAT1 than the human liver cell line." (PMID 31168355, 2019). "In oncology, Wang and colleagues found that the lncRNA MALAT1 is a biomarker for bladder carcinoma, Xie and his colleagues found that the lncRNA HULC is a biomarker for hepatocellular carcinoma, and Zhou and colleagues found that the lncRNA H19 is a possible diagnostic marker for gastric cancer." (PMID 29463949, 2017). "For instance, the lncRNA metastasis-associated lung adenocarcinoma transcript 1 (MALAT1) plays a role in the metastatic potential of not only lung adenocarcinomas, but also hepatocellular carcinoma, colonic cancer and bladder cancer." (PMID 28003470, 2016). "MALAT1 is localized in nuclear speckles and widely expressed in normal tissues, but was found to be upregulated in hepatocellular carcinoma, breast, pancreas, osteosarcoma, colon and prostate cancers." (PMID 23443164, 2013). "In sorafenib-resistant hepatocellular carcinoma (HCC), NSUN2 cooperates with ALYREF to maintain the stability and high expression of the long non-coding RNA MALAT1 via its m5C methyltransferase activity." (PMID 41256859, 2025). "Analysis of TCGA data from 369 hepatocellular carcinoma (HCC) patients and 50 healthy controls using the GEPIA2 database revealed that the expression level of MALAT1 in tumor tissues was significantly higher than that in normal tissues." (PMID 40958861, 2025). "Moreover, arsenite promotes MALAT1 and HIF-2α expression in hepatoma cells." (PMID 30477236, 2018). "In addition to OC, MALAT1 has been also proposed as a prognostic marker for CRC, hepatocellular carcinoma (HCC), squamous cell lung cancer, BC, GC, esophageal cancer, and osteosarcoma." (PMID 37373222, 2023). "Besides, MALAT1 could bind miR-200s to regulate ZEB2 in ccRCC, while LncRNA-ATB could regulate ZEB1 and ZEB2 by competitively binding the miR-200s to control EMT and invasion in hepatoma cells." (PMID 29156724, 2017). "Recent studies have shown that MALAT1 enhances the expression of serine-rich arginine splicing factor 1 (SRSF1) and activates the mammalian rapamycin target (mTOR) signaling pathway to promote the formation of gastric cancer (GC) and hepatocellular carcinoma (HCC)." (PMID 35208500, 2022).
colorectal cancer (173 papers, 2013 to 2026). A primary or metastatic malignant neoplasm that affects the colon or rectum. "Metastasis-associated lung adenocarcinoma transcript-1 (MALAT1) promotes colorectal cancer cell proliferation, migration, metastasis, and angiogenesis by targeting several genes and signaling pathways, including WNT/β-catenin, Snail, PI3K/AKT/mTOR, PERK/ATF4." (PMID 38374003, 2024). "This study investigated the relationship between the long non-coding RNA Metastasis-Associated Lung Adenocarcinoma Transcript 1 (MALAT1) expression and colorectal cancer (CRC) using a thorough systematic review and meta-analysis." (PMID 39471147, 2024). "High levels of Linc00152 and MALAT1, for instance, have been linked to oxaliplatin resistance in colorectal cancer." (PMID 37013584, 2023). "lncRNAs KCNQ1OT1, HOX transcript antisense RNA (HOTAIR), and metastasis-associated lung adenocarcinoma transcript 1 (MALAT1) have been dysregulated in colorectal cancer." (PMID 38094755, 2023). "Similar to human colorectal cancers, MALAT1 is slightly downregulated in the murine colonic polyps compared to healthy tissues, a pattern also observed in genes encoding known colorectal cancer tumor suppressor molecules, such as Mbd1 and Tmigd1." (PMID 37325561, 2023). "For example, long non-coding RNA metastasis-associated lung adenocarcinoma transcript 1 (LncRNA MALAT1) heightens the proliferation, migration, and drug sensitivity of colorectal cancer cells by negatively regulating miR-20b-5p." (PMID 34968160, 2022). "Prognostic associations of MALAT1 expression and colorectal cancer outcomes in the external validation population." (PMID 35558512, 2022). "Prognostic associations of MALAT1 expression and colorectal cancer outcomes in the initial population." (PMID 35558512, 2022). "Prognostic associations of MALAT1 expression and colorectal cancer outcomes in the combined populations." (PMID 35558512, 2022). "Studies found the lncRNA-MALAT1 (metastasis-associated lung adenocarcinoma transcript 1) upregulated expression in colorectal cancer and correlated with the tumor grade and metastatic spread." (PMID 34715919, 2021). "Another MALAT1 SNP rs1194338 was also identified as a protective factor toward colorectal cancer susceptibility (OR = 0.70, 95% CI = 0.49–0.99, p = 0.045)." (PMID 34574033, 2021). "Another lncRNA, the Metastasis-Associated Lung Adenocarcinoma Transcript 1 (MALAT1), is also upregulated in lung and colorectal cancers." (PMID 34359809, 2021). "Human metastases-associated lung adenocarcinoma transcript 1 (MALAT1) is a long non-coding RNA known to promote cell proliferation, metastasis, and invasion in colorectal cancer (CRC)." (PMID 32209115, 2020). "The authors demonstrated that MALAT1 with the rs664589 G allele had altered binding to miR‐194‐5p in the nucleus, leading to increased MALAT1 expression and enhanced colorectal cancer development." (PMID 31880028, 2020). "In fact, in colorectal cancer, high levels of MALAT1 have been associated with increased proliferation and migration, whereas in esophageal cancer, it promotes epithelial-to-mesenchymal transition through the modulation of the Notch pathway." (PMID 33375130, 2020). "In colorectal cancer, MALAT1 has been associated with increased proliferation and migration; and recently has been shown to regulate the metabolic transcription factor TCF7L2, which promotes metabolic reprogramming relevant for HCC tumor progression." (PMID 33375130, 2020). "MALAT1 has been implicated in colorectal cancer metastasis and bladder cancer cell migration, highlighting its ability to participate in in carcinogenesis." (PMID 31174563, 2019). "Some studies reported that MALAT1 inhibited E-cadherin expression by binding to highly expressed EZH2 at its 3′ end in colorectal cancer, thereby caused tumor cell epithelial-mesenchymal transition (EMT) and oxaliplatin resistance." (PMID 31391118, 2019).
colorectal cancer (continued). "MALAT1 is associated with poor response to oxaliplatin-based chemotherapy in colorectal cancer patients and promotes chemoresistance through EZH2." (PMID 29212230, 2017). "MALAT1 is also associated with poor prognosis to oxaliplatin-based chemotherapy in colorectal cancer patients and promotes chemoresistance through EZH2." (PMID 29212230, 2017). "Moreover, miR-101-3p plays a critical role in overcoming therapy resistance, as it counteracts the tumor-enhancing effects of MALAT1, a long noncoding RNA associated with increased survival and radioresistance in colorectal cancer cells." (PMID 40227597, 2025). "In addition, JMJD2C protein entering the nucleus improved the -linked protein signaling pathway in colorectal cancer cells by lowering H3K9me3 and H3K36me3 histone methylation levels in the MALAT1 promoter region and upregulating MALAT1 expression." (PMID 36118885, 2022). "In addition, an in vitro study revealed that lnc MALAT1 (metastasis-associated lung adenocarcinoma transcript 1 lncRNA) has an abnormally high level of expression in colorectal cancer tissues." (PMID 36291546, 2022). "Previous researches have shown that the aberrant expression of Metastasis associated in lung adenocarcinoma transcript 1 (MALAT1) in tumour tissues may serve as a biomarker for colorectal cancer (CRC) prognosis." (PMID 35558512, 2022). "Furthermore, MALAT1-mediated tumor metastasis has been associated with chemoresistance in gastric, lung, cervical, ovarian, and colorectal cancers, and the underlying mechanisms were associated with different cell signaling pathways." (PMID 32708561, 2020). "Also, to the best of our knowledge, no studies have still focused on the association between the methylation in the promoter of MALAT1 and the risk of colorectal cancer." (PMID 32099603, 2019). "However, there is insufficient information on the association between MALAT1 and the methylation process as well as its role in the development of colorectal cancer." (PMID 32099603, 2019). "However, no study has been performed to investigate the relationship between the genetic variants in promoter region of MALAT1 and colorectal cancer risk." (PMID 29190941, 2017). "In this study, we conducted a two-stage case-control study to evaluate whether MALAT1 genetic variants were associated with colorectal cancer risk." (PMID 29190941, 2017). "Furthermore, resveratrol can inhibit the invasion and metastasis of colorectal cancer cells through metastasis associated lung adenocarcinoma transcript 1 (MALAT1) mediated Wnt/β-catenin signal pathway." (PMID 28119606, 2016). "Moreover, the 3′-end portion of MALAT1 is not only found highly mutated in colorectal cancer cells, but has also been shown to be essential in various biological processes such as cell proliferation, migration and invasion." (PMID 26516927, 2015). "According to the information obtained in our study, we examined the association between MALAT1 gene promoter methylation pattern and clinicopathologic factors including family history of colon cancer, tumor site, size, grade and stage in 20 patients with colorectal cancer." (PMID 32099603, 2019). "In colorectal cancer, MALAT1 facilitates tumor cell proliferation while inhibiting apoptosis through autophagy activation, underscoring its pivotal role in tumor cell survival." (PMID 41584724, 2026). "mtr-miR-5754 and gma-miR4995 directly target the tumor-associated long non-coding RNA MALAT1 and NEAT1 and attenuate proliferation of colorectal cancer cells." (PMID 40149445, 2025). "A mixture of seven plant miRNAs inhibited proliferation of colorectal cancer cells and suppressed expression of the oncogenic lncRNAs MALAT1 and NEAT1." (PMID 40149445, 2025). "Knocking down MALAT1 significantly reduces proliferation and invasiveness of colorectal cancer cells in laboratory studies." (PMID 39830506, 2024).
colorectal cancer (continued). "Colorectal cancer-associated transcript (CCAT), H19, metastasis-associated lung adenocarcinoma transcript 1 (MALAT-1), and HOX transcript antisense intergenic RNA (HOTAIR) are among them; they are the most representative lncRNAs." (PMID 38294554, 2024). "Overexpression of MALAT1 has been consistently observed across various cancer types, encompassing colorectal cancer, prostate cancer, pancreatic cancer, and BC, among others." (PMID 39323624, 2024). "The manipulation of MALAT1-mediated pathways offers a critical therapeutic strategy for colorectal cancer." (PMID 38374003, 2024). "Summary of findings for meta-analysis of colorectal cancer histopathological characteristics based on MALAT1 expression." (PMID 39471147, 2024). "Specific lncRNAs, such as MALAT-1, HOTAIR, LINC00152, and others, have shown diagnostic potential in prostate, lung, colorectal, hepatocellular, gastric, renal, and colorectal cancers." (PMID 39132504, 2024). "In colorectal cancer, MALAT1, a competing endogenous RNA, sponges miR-20b to partially regulate the expression of OCT4, thereby promoting maintenance of stemness." (PMID 38254118, 2024). "The downregulation of MALAT1 enhanced the sensitivity of the human colorectal carcinoma cell line HCT-116 to 5-fluorouracil by targeting miR-20b-5p." (PMID 39471147, 2024). "Subsequent investigations have unveiled that the activated IRE1 and PERK signaling pathways enhance the expression of MALAT1, subsequently fostering colorectal cancer (CRC) cell migration." (PMID 38066437, 2023). "Our study identified that MALAT1 promotes colorectal cancer resistance to oxaliplatin by reducing the miR-200s expression." (PMID 36248422, 2022). "The inhibition pathway MALAT1/miR-145/SOX9 thus promotes colorectal cancer cell growth, migration, and invasion." (PMID 35887000, 2022). "Among other miRNAs, that are target of MALAT1 in relation to colorectal cancer progression, are also miR-508–5p, miR-324-3p, miR-363–3p, and miR-129-5." (PMID 35887000, 2022). "Metastasis-associated lung adenocarcinoma transcript 1 (MALAT1) is a long and highly expressed non-coding RNA sequence in many tumors, such as colorectal cancer." (PMID 34943833, 2021). "In colorectal cancer, instead, MALAT1/NEAT2 triggers tumor growth and metastasis by binding to the splicing factor SFPQ causing the subsequent disruption of the splicing regulator complex SFPQ-PTBP2 and the release of the oncogene PTBP2." (PMID 33799493, 2021). "Silencing MALAT1 suppresses colorectal cancer cell proliferation as well as expression levels of EZH2 by upregulating miR-363-3p." (PMID 34660566, 2021). "Our Targetscan prediction results revealed that miR-202-3p targeted SRSF1, which was further confirmed by the RNA pull-down and RIP experiments Consistently, SRSF1 has reported being activated by MALAT1 in colorectal cancer cells." (PMID 34001131, 2021). "In colorectal cancer, lncRNA MALAT1 can sponge miR-106b-5p and enhanced microtubule migration via SLAIN2 to promote invasion and metastasis." (PMID 34888249, 2021). "A SNP located in the lncRNA MALAT1 has been shown to inhibit binding of the lncRNA to miR-194-5p, resulting in increased expression of MALAT1 and contributing to colorectal cancer development." (PMID 33499210, 2021). "For instance, MALAT-1 expression was distinctly upregulated in colorectal carcinoma, and its knockdown suppressed colorectal carcinoma cells' metastasis and proliferation via sponging miR-203/DCP1A axis." (PMID 34858541, 2021). "Another study showed that compounds such as resveratrol regulate MALAT1 expression in colorectal cancer (CRC) cells and inhibit tumor metastasis via the Wnt/β-catenin pathway." (PMID 31733641, 2020). "In colorectal cancer tissues from patients receiving oxaliplatin-based chemotherapy, high levels of MALAT1 correlate with resistance to oxaliplatin treatment and poor patient survival." (PMID 32174966, 2020).